CTLA4 (cytotoxic T-lymphocyte associated protein 4)
Diseases named in the same sentence as CTLA4 in open-access papers (continued):
Sharing a sentence is not in itself a finding about the gene and the disease.
cancer (continued). "T cells are critical mediators of natural antitumor immunity which can be leveraged by TIL therapy or immune checkpoint blocking (ICB) therapy, such as antibodies directed against PD-1/L1 and CTLA-4 that established cancer immunotherapy as a pillar of cancer care a decade ago." (PMID 35129050, 2022). "YST-OVH also synergized with CTLA-4 or TIM-3 blockade to enhance the immune response to cancer." (PMID 35688558, 2022). "Despite the success of anti-PD1/PD-L1 and anti-CTLA4 therapies in advanced cancer." (PMID 35874717, 2022). "Targeting immune-checkpoint molecules, such as programmed cell death 1 (PD-1), programmed cell death ligand 1 (PD-L1) and cytotoxic T-lymphocyte-associated protein 4 (CTLA-4), has also demonstrated to be one of the most promising cancer treatments, with positive results in KRAS-mutated cancers." (PMID 35883626, 2022). "False discovery rates of the significance for each of the enhanced pathways are: 0.0015 for PD-L1 expression and PD-1 checkpoint pathway in cancer, 0.0029 for cancer immunotherapy by CTLA4 blockade, 0.0053 for cancer immunotherapy by PD-1 blockade, and 0.0081 for PD-1 signaling." (PMID 36551790, 2022). "Cancers may evade immune surveillance by utilizing immune checkpoint genes including PD-1, CTLA-4 and PD-L1." (PMID 36160408, 2022). "One of the strategies that can be employed to overcome these obstacles of using immune checkpoint inhibitors (such as anti-PD-L1, anti-PD-1 and anti-CTLA-4) in cancer therapy is to utilize immune checkpoint inhibitors in combination with oncolytic adenoviruses." (PMID 35756634, 2022). "Tumor microenvironment cells also concur to anti-cancer immune escape through the expression of inhibitor receptors on cancer and immune surface, such as the programmed death-ligand 1 and 2 (PD-L1, PD-L2) and the CTLA-4." (PMID 35849879, 2022). "Via the Cancer Immunome Atlas (TCIA) database, lower expression of DLX2 was also found to be associated with better IPS score of PD-1/PD-L1 blockade (p < 0.001) as well as CTLA-4 combined with PD-1/PD-L1 blockade (p < 0.001)." (PMID 36317140, 2022). "In addition, the blockade of immune checkpoint inhibitors (ICIs), including PD1, PDL1, and CTLA4, has improved cancer patient survival outcomes." (PMID 36611894, 2022). "The positive effects of tretinoin could be extended to ICT antibodies targeting OX40, GITR and CTLA4 monotherapy in multiple cancer models." (PMID 35402250, 2022). "Thus, expansion of the existing ideas about the role of CTLA-4 may lead to the development of new approaches to improve the quality of diagnosis and provide further insights into fundamental mechanisms underlying targeted therapy of cancer and other pathological conditions." (PMID 33925389, 2021). "There is increasing evidence hinting that inhibition of glycolysis could effectively improve the response of cancer cells to CTLA-4 blocker by impairing the stability of Treg cells." (PMID 34886901, 2021). "Exhausted T cells could produce additional inhibitory molecules to promote the progression of cancer; however, this process could be reversed by a combined PD-1 and CTLA-4 blockade." (PMID 34912710, 2021). "Immune checkpoint inhibitors (ICIs) greatly enhanced cancer treatment, yet many patients are intrinsically resistant to anti-programed cell death protein 1 (anti-PD1) and anti-cytotoxic T-lymphocyte-associated protein 4 (anti-CTLA4) therapies or they become resistant after initial response." (PMID 34944932, 2021). "It has been unclear whether there are sex-related differences in the therapeutic benefits of PD-1/PD-L1 or CTLA-4 inhibitors for cancer treatment." (PMID 34086601, 2021). "As two checkpoints of cancer immunotherapy, PD-1 and CTLA-4 have attracted our attention." (PMID 34721758, 2021). "However, CTLA4 exists in the cytoplasm in both normal and cancer cells to a much larger extent than CTLA4 expressed on the cellular membrane." (PMID 34064074, 2021).
cancer (continued). "Ipilimumab was the first anti-CTLA-4 to be studied and used in cancer treatment." (PMID 33650838, 2021). "Inhibition of the two best described immune checkpoints, CTLA-4 and PD-1, using monoclonal antibodies has led to a breakthrough in cancer immunotherapy in the recent decade, showing remarkable responses and improved overall survival (OS) in many different solid tumors." (PMID 33746972, 2021). "Monoclonal antibodies directed against programmed cell death 1 (PD-1), programmed cell death 1 ligand 1 (PD-L1) or cytotoxic T-lymphocyte associated protein 4 (CTLA-4), also known as immune checkpoint inhibitors, have significantly improved the therapy of various cancers." (PMID 34016720, 2021). "In recent years, inhibitors of CTLA-4 have shown remarkable success in cancer immunotherapy." (PMID 34305910, 2021). "Immunotherapy aims at reactivating repressive immune cells of cancer patients and acquires exciting results, especially for immune checkpoint blockers of immune monoclonal antibodies, such as PD-1 antibody, PD-L1 antibody, as well as CTLA-4 antibody." (PMID 34568317, 2021). "Immune-checkpoint inhibitors (ICIs) targeting cytotoxic T lymphocyte-associated antigen 4 (CTLA-4), programmed cell death 1 (PD-1) and its ligand (PD-L1) interaction have shifted the treatment landscape of advanced cancers and significantly improved the overall survival (OS)." (PMID 34248939, 2021). "Since the FDA approved Ipilimumab which is a human CTLA-4 blocking antibody and alters the adaptive immune system for the treatment of melanoma in 2011, cancer immunotherapy has become an epoch-making achievement and has achieved some exciting clinical applications." (PMID 34568317, 2021). "The focus of this article is on the CTLA-4-positive population of Treg cells in cancer." (PMID 33809974, 2021). "A better understanding of the biological mechanisms and functions of negative and positive co-stimulatory molecules has been shown to be essential for improving current and potentially new CTLA-4 or Programmed Cell Death 1 (PD-1) inhibitors for anti-cancer immunotherapies." (PMID 33809974, 2021). "Inhibitory checkpoint molecules expressed on T cells, including program death 1 (PD-1) and cytotoxic T lymphocyte-associated antigen 4 (CTLA-4), are typical key negative regulators of T cell-mediated immune response and therefore are considered as targets for cancer immunotherapy." (PMID 34369137, 2021). "While our study is computationally focused, the application of our transfer learning pipeline for cross-species analysis to cancer immunotherapy still suggests that the role of NK cells in anti-CTLA-4 response is preserved between preclinical mouse models and human tumors." (PMID 34376232, 2021). "Importantly, anti-PD-1, anti-PD-L1, and anti-CTLA-4 antibodies have contributed to the huge success in treating a considerable number of patients with various cancer types." (PMID 34360800, 2021). "Additionally, the loss of β2 m represents resistance to checkpoint blockades cytotoxic T lymphocyte-associated protein 4 (CTLA-4) and (programmed cell death protein 1) PD-1 blockade in cancers." (PMID 34827170, 2021). "CTLA-4/B7 and PD-1/ PD-L1 axis regulate physiological immune homeostasis, downregulate inflammatory responses, and presumptively facilitate immune evasion of cancer cells." (PMID 34088360, 2021). "When bound to its ligands CD80 or CD86 on the surface of various immune cells including B cells, monocytes and antigen-presenting cells, such as macrophages and dendritic cells, CTLA-4 downregulates immune responses preventing the immune system from killing cancer cells." (PMID 33925389, 2021). "Indeed, the combination of Ipilimumab (anti-CTLA-4) and Nivolumab (anti-PD-1) significantly enhanced efficacy in metastatic melanoma patients and probably is more effective in other cancers than monotherapies." (PMID 33717139, 2021).
cancer (continued). "We used the clinically validated Ipilimumab and Nivolumab and other novel human antibodies targeting Cytotoxic T- lymphocyte-antigen 4 (CTLA-4), Programmed Death receptor-1 (PD-1) and Programmed Death Ligand 1 (PD-L1) to shed light on the functions of these ICs in cancer cells." (PMID 34201082, 2021). "In conclusion, most studies have shown that anti-CTLA-4 antibodies mainly depleted Treg cells in cancers, whereas very few have observed that the number of Treg cells increased or remained the same because of different experimental settings or in some cases, the design of their therapeutic agents." (PMID 33809974, 2021). "Indeed, the development of checkpoint inhibitors, such as anti-CTLA4, anti-PD-1, and anti-PD-L1, has brought remarkable success in cancer immunotherapy." (PMID 34065346, 2021). "The discovery of the immune checkpoints, Programmed cell death protein (PD-1) and Cytotoxic T-lymphocyte-associated protein 4 (CTLA-4) and their role in cancer immunology represent promising developments in oncotherapeutics, recognised by the Nobel Prize in 2018." (PMID 34302062, 2021). "In addition to multiple studies focusing on anti-PD1/PD-L1 and anti-CTLA4 antibodies, other immune co-inhibitory and co-stimulatory agents are being actively studied to enhance the efficacy of cancer vaccines." (PMID 34579759, 2021). "Using CRISPR/Cas9 technology to knock out immune checkpoints such as programmed death-1 (PD-1), programmed cell death ligand 1 (PD-L1) and cytotoxic T-lymphocyte antigen 4 (CTLA-4) may provide a new direction for cancer immunotherapy." (PMID 35111663, 2021). "Despite the lack of correlation between CTLA-4 ligand expression and a specific cancer cell type and the fact that Ctla-4-knockout mice models predicted lethal autoimmune phenotypes, it was shown that CTLA-4 inhibition produced antitumoral responses in preclinical cancer models." (PMID 34168976, 2021). "Seven immune checkpoints inhibitors have so far received FDA approval for use with different types of cancer: one CTLA-4 inhibitor (ipilimumab), three PD-1 inhibitors (nivolumab, pembrolizumab, and cemiplimab) and three PD-L1 inhibitors (atezolizumab, durvalumab, and avelumab)." (PMID 34680282, 2021). "Finally, the immunophenoscore (IPS) based on The Cancer Immunome Atlas (TCIA) database was used to predict responsiveness to CTLA-4 and PD-1." (PMID 34925377, 2021). "In addition, these results suggested that anti-CTLA4 drugs blocking immune checkpoints leads to T-cell activation, which is an ideal strategy for treating cancer." (PMID 33758613, 2021). "Based upon all the results from the literature, administration of a‐PD‐L1 and a‐CTLA‐4 blockade combined with CSCs‐targeted CAR‐T cells may be an effective immunotherapeutic strategy for cancer patients." (PMID 34585512, 2021). "Thus, the role of CTLA-4 inhibitors in the development of NP in cancer patients would be of interest." (PMID 34331199, 2021). "Immune checkpoint inhibitors such as anti-Programmed Cell Death Protein (PD1), anti-Programmed Death-Ligand 1 (PD-L1), and anti-Cytotoxic T-Lymphocyte Protein 4 (CTLA-4) have recently been approved for cancer treatment use due to their potent antitumor effects." (PMID 34205328, 2021). "After the notable achievements for cancer therapy by the use of blocking the CTLA-4 and PD-1, which are the first detected immune checkpoints, a new surge of explorations for cancer therapy based on the blocking of immune checkpoint ligands and receptors, was emerged." (PMID 32902664, 2021). "Currently antibodies targeting cytotoxic T lymphocyte associated protein 4 (CTLA4) and the programmed cell death protein 1 and its ligand (PD-1, PD-L1) are utilised clinically, and T cell modulators are indicated for treatment of c.50 cancer types." (PMID 34688033, 2021). "Recently, CTLA-4 has become a major targeting site for cancer therapy." (PMID 35008249, 2021).
cancer (continued). "Furthermore, inhibitory proteins, including programmed death receptor-1 (PD-1) and cytotoxic T-lymphocyte-associated antigen-4 (CTLA-4), also mediate immune evasion of cancer cells." (PMID 34400888, 2021). "Furthermore, immune checkpoint inhibitors, such as anti-CTLA-4 or anti-PD-1, in cancer treatment also induce hypersensitivity reactions including SJS/TEN and DRESS/DIHS." (PMID 33717075, 2021). "Immunotherapy has demonstrated great potential in treating a variety of cancers, in particular immune checkpoint inhibitors (ICI) targeting cytotoxic T-lymphocyte-associated protein 4 (CTLA-4) or Programmed death-ligand 1 (PD-L1)/Programmed cell death protein 1(PD-1)." (PMID 34966689, 2021). "Interestingly, besides PD-1, also the immune-checkpoint Cytotoxic T lymphocyte-associated antigen 4 (CTLA-4), classically expressed on leukocytes, has been found to be expressed and functional on cancer cells." (PMID 33413561, 2021). "Eventually, the effects of CTLA-4 were studied in other cancers, including HCC." (PMID 34440865, 2021). "In most cancer types, the expression of immune checkpoint receptors, such as PD-1, CTLA-4, TIM-3, Lag-3, and other inhibitory molecules in CD8+ T cells is associated with the disease prognosis and is highly predictive of efficient immunotherapy with immune checkpoint inhibitors (CPIs)." (PMID 34440139, 2021). "The immunotherapy targeting cytotoxic T lymphocyte-associated protein 4 (CTLA4) and programmed cell death 1 (PD-1) has recently been demonstrated to be an effective approach to activate immune response and treat a wide range of cancers." (PMID 34830445, 2021). "Indeed, the satisfactory results of CTLA-4 inhibitors in rejecting various tumors have translated into the FDA’s approval to treat patients with cancers." (PMID 34067631, 2021). "Additionally, CTLA-4 blocking promotes antitumor responses through the deletion of Tregs via antibody mediated cytotoxicity, as demonstrated in murine cancer models." (PMID 33406696, 2021). "The epigenetic signature was also highly correlated with the expression of CTLA4, PD-L1, and PD-1, suggesting that it may be a potential indicator of cancer immune infiltration and may predict the patients’ response to immunotherapy drugs." (PMID 34136486, 2021). "CTLA-4 was first cloned in 1987 as a novel molecule expressed on activated T cells and was later shown to have an inhibitory function; in 1996, it was found that the CTLA-4 antibody could suppress cancer growth in the mouse model." (PMID 34071550, 2021). "Modulators of immune checkpoints, namely antibodies targeting PD-1 (Pembrolizumab, Nivolumab and Cempilimab), PD-L1 (Atezolizumab, Avelumab or Durvalumab) or CTLA4 (Ipilimumab) are at the vanguard of a reinvigorated approach to harness the immune system to kill human cancers." (PMID 35006469, 2021). "Thus, the expression profile of soluble CTLA-4 reflects its apparent role in adaptive immune responses and involvement in immune evasion of cancer cells." (PMID 34531847, 2021). "In addition, specific immune checkpoint inhibitors such as CTLA-4, PD-1, and PD-L1 have dramatically changed the current status of cancer treatment and are beneficial for the overall survival (OS) of a variety of patients with cancer." (PMID 34745261, 2021). "Moreover, it was also observed that cancer patients receiving anti-CTLA4 and/or anti-PD-1 immunotherapy suffered from more drug hypersensitivity adverse events." (PMID 33717075, 2021). "More recently, Alison and Honjo, the 2018 Nobel prize winners in physiology, discovered immune checkpoint proteins, such as programmed cell death protein-1 (PD-1) and cytotoxic T lymphocyte antigen 4 (CTLA-4), which are key negative regulators of the immune system and cancer growth." (PMID 33466394, 2021).
cancer (continued). "Although antibodies against the co-inhibitory receptors, cytotoxic T lymphocyte antigen 4 (CTLA-4) and programmed cell death 1 (PD-1), exhibit prominent efficacy in several cancer indications, only 20% of cancer patients respond to single-agent checkpoint inhibitors." (PMID 34708061, 2021). "For example, Immune checkpoint inhibitors (PD1/PD-L1, CTLA-4) have achieved certain success in cancer treatment by block the immune evasion of cancer cells but they are limited in clinical applications mainly due to large individual variations and low therapeutic responses (about 20%)." (PMID 33401518, 2021). "Moreover, immune checkpoint CTLA-4 on the surface of Tregs bind to their targets on anti-cancer immune cells, and inhibit their functions." (PMID 35111682, 2021). "This drug may have great potential in the treatment of cancer patients in combination with other immunotherapies (e.g., anti-CTLA-4), in first-line monotherapy, and in combination with chemotherapy." (PMID 34200219, 2021). "Cancer cells can escape immunosurveillance through immune suppression by expressing ligands for co-inhibitory receptors such as programmed death-1 (PD-1) or cytotoxic T-lymphocyte protein 4 (CTLA-4)." (PMID 34948368, 2021). "Zappasodi and co-author researched the effect of CTLA-4 blockade on the metabolic fitness of intratumor T cells in relation to the glycolytic capacity of cancer cells, finding that CTLA-4 blockade promotes metabolic fitness and the infiltration of immune cells." (PMID 35008249, 2021). "Here, we have summarized the role of intestinal microbiota in clinical trials related to cancer immunotherapy and generated a schematic representation of the degree of correlation between intestinal microbiota and immune checkpoints (PD-1/PD-L1 and CTLA-4)." (PMID 34125407, 2021). "Similarly, CTLA-4 expression, specifically regulated by its localization within the cell, regulates anti-cancer responses." (PMID 34088360, 2021). "ICIs that target PD-1, its ligands, or CTLA-4 have changed the way cancer is treated worldwide." (PMID 35047501, 2021). "Several factors may influence the development of irAEs during treatment with ICIs, including the cancer type, molecular target (CTLA-4 or PD-1/PD-L1), single agent administration or combined checkpoint blockade and/or sequential use of different types of ICIs." (PMID 34790123, 2021). "Additionally, Treg downregulates the level of IL-2 and upregulates the level of programmed death-1 (PD-L1), T-cell immunoglobulin mucin-3 (TIM-3), and cytotoxic T-lymphocyte-associated protein 4 (CTLA-4) etc. and stimulates cancer immune escape." (PMID 34885253, 2021). "In chronic inflammatory conditions such as cancer, prolonged T cell activation leads to increased CTLA-4-expressing Tregs and upregulation of CTLA-4 on cytotoxic T lymphocytes (CTLs), which interacts with the B7 family of receptors and leads to reduced T cell proliferation and survival." (PMID 34054867, 2021). "Furthermore, blockade of immune checkpoints such as PD-1/PD-L1 and CTLA-4 has been trendy in malignant tumors." (PMID 34539641, 2021). "The value of this pioneering work is now becoming more and more evident with the importance of the immune system in the fight against cancer with another T-cell receptor activation related molecule, CTLA4, as recognized and highlighted by the work of James Allison." (PMID 35201440, 2021). "Novel therapy targeting immune checkpoints, such as programmed cell death 1 (PD1)/programmed cell death 1 ligand 1 (PD-L1), cytotoxic T-lymphocyte associated protein 4 (CTLA4) and T-cell membrane protein 3 (TIM3) have made breakthrough in many types of cancer treatment." (PMID 34249934, 2021). "CTLA4 and PD-1 are two important immune checkpoint molecules in cancer immunology." (PMID 33406733, 2021). "In addition to CTLA-4 and PD-1, “second-generation” coinhibitory receptors and ligands that belong to the B7 family are emerging as potential new targets in cancer immunotherapy." (PMID 33717075, 2021).